SDHD (succinate dehydrogenase complex subunit D)
Diseases named in the same sentence as SDHD in open-access papers (continued):
Sharing a sentence is not in itself a finding about the gene and the disease.
pheochromocytoma (continued). "Germline mutations of the SDHD, SDHB and SDHC genes, encoding three of the four subunits of succinate dehydrogenase, are a major cause of hereditary paraganglioma and pheochromocytoma, and demonstrate that these genes are classic tumor suppressors." (PMID 16405730, 2006). "We show here that pheochromocytomas with VHL and SDHB or SDHD mutations form a tight cluster with a clear hypoxia and reduced oxidoreductase signature." (PMID 16103922, 2005). "Familial phaeochromocytoma or head and neck paraganglioma (HNPGL) kindreds with germline SDHD mutations demonstrate parent-of-origin effects on penetrance." (PMID 15505628, 2004). "Although genetic and physiopathological aspects of SDHD mutations have been deeply studied, current pheochromocytomas and PGLs clinical guidelines do not focus specifically on the clinical management of FPGL1 patients." (PMID 32098148, 2020). "Phaeochromocytomas and paragangliomas have been paradigm shifters in genetic studies, being the first human tumour model recognised to carry a genetic defect in a metabolic enzyme (SDHD) two decades ago." (PMID 29166454, 2017). "The major mutations associated with pheochromocytoma are von Hippel-Lindau gene (VHL), REarranged during Transfection (RET) proto-oncogene, neurofibromatosis type 1 gene (NF1), genes encoding four succinate dehydrogenase complex subunits (SDHx; i.e., SDHA, SDHB, SDHC, and SDHD genes)." (PMID 35932074, 2022). "Familial HNPGLs together with pheochromocytomas (PCCs) account for about 40% and are associated with four types of hereditary paraganglioma syndromes (PGL1–5) caused by mutations in the following genes: SDHD (PGL1), SDHAF2 (PGL2), SDHC (PGL3), SDHB (PGL4), and SDHA (PGL5)." (PMID 33391357, 2020). "Moreover, recent studies indicate that up to 25% of pheochromocytoma patients have a genetic background (NF1, VHL, SDHD, SDHB or RET gene mutations) and thus both the patients and their closest blood relatives require wide multidisciplinary diagnostics as well as long-term follow-up." (PMID 31137898, 2019). "It is now known that SDHB and SDHD, together with VHL and RET, play a major role in hereditary pheochromocytoma." (PMID 16405730, 2006). "In this study, it was found that 24% of the patients who presented with nonsyndromic pheochromocytoma and without family history of the disease had mutations in VHL, RET, SDHD, and SDHB genes." (PMID 24899893, 2014). "Recent evidence suggests that additional genetic factors located on chromosome 11 may, together with SDHD, play a role in the tumorigenesis of HN PGL and pheochromocytoma." (PMID 16288654, 2005).
leprosy (49 papers, 2010 to 2026). Leprosy is a chronic infectious disease affecting primarily the skin and peripheral nervous system. "The protein interaction network analysis supported this speculation, as we found that the other mitochondrial genes (MCCD1, SDHD, SNCA, and VARS2) could interact with the reported leprosy susceptibility genes." (PMID 27876828, 2016).
head and neck paraganglioma (21 papers, 2004 to 2025). A benign or malignant extra-adrenal paraganglioma arising from paraganglia in the head and neck. "As expected, our study showed a significantly higher risk of developing head and neck paragangliomas in SDHD variant carriers compared with other SDHx genes." (PMID 39881751, 2025). "Among the SDHD variant carriers, the risk of developing a head and neck paraganglioma was 17.5% (confidence interval [CI]: 15.9–19.1) after 5 years, 62.9% (CI: 33.5–92.3) after 10 years, and 82.4% (CI: 52.8–112.0) after 15 years." (PMID 39881751, 2025). "It is known that SDHD mutation is more often associated with head and neck paragangliomas, and FANCA mutation is associated with Fanconi anaemia." (PMID 39673085, 2024). "Head and neck paragangliomas are the most common clinical features of familial paraganglioma syndrome type 1 caused by succinate dehydrogenase complex subunit D (SDHD) mutation." (PMID 32098148, 2020). "Inactivating mutations in the SDHD gene, autosomal-dominantly acquired, give rise to familial parasympathetic head and neck paragangliomas." (PMID 29166454, 2017). "Multiple head and neck paragangliomas are common in patients with SDHD mutations, while malignant head and neck paraganglioma is mostly seen in patients with SDHB mutations." (PMID 26543766, 2015). "Together with our previous study of SDHD mutations we have now found 27 SDH germline mutations in 95 cases (28%) of sporadic head and neck paraganglioma, the majority of these being Dutch founder mutations of SDHD." (PMID 16405730, 2006). "Previously we reported the frequency of SDHD mutations in familial and sporadic head and neck paraganglioma in the Netherlands." (PMID 16405730, 2006). "One patient with a metastatic head and neck paraganglioma that was associated with a germline SDHD mutation experienced SD for 24 months; during the last month of therapy with pembrolizumab, the patient developed a pathologic fracture of the spine that was related to tumor progression." (PMID 32824391, 2020). "Of these 32 patients, 71.8% had primary extra-adrenal tumors with genetic analysis demonstrating germline SDHB mutations in 71.9% of patients, SDHD mutations in 9.4% of patients (found in all patients with head and neck paraganglioma), and VHL mutations in 6.3% of patients." (PMID 30456751, 2018). "In line with this hypothesis, recently H19, a paternally imprinted gene on 11p15, has been put forward as the tumor suppressor gene responsible for the parent-of-origin dependent inheritance in SDHD -linked head and neck paragangliomas." (PMID 19432956, 2009). "Previous studies of mutations of SDH genes related to sporadic head and neck paraganglioma have examined SDHB, C, and D together or SDHD only." (PMID 16405730, 2006). "Including our previous results, we have screened a total of 95 sporadic head and neck paraganglioma cases for germline mutations of SDH genes and found 24 (25%) in SDHD, 2 (2%) in SDHB and 1 (1%) in SDHC (total = 28%)." (PMID 16405730, 2006). "Data regarding SDHC mutation carriers are scarce but these carriers seem to present predominantly with non-metastatic head and neck paragangliomas with a lower rate of multiplicity and a lower penetrance than people who have an SDHD mutation." (PMID 34021277, 2021). "An even rarer cause for head-and-neck paraganglioma is the SDHAF2 mutation, which should be considered if SDHD, SDHB, and SDHC testing is negative." (PMID 29166454, 2017). "No significant differential expression between sporadic, SDHD and PGL2 -linked head and neck paragangliomas was observed for this gene set (data not shown)." (PMID 19432956, 2009).
metastatic disease (14 papers, 2018 to 2026). "No mutations were detected in the genetic tests for SDHB and SDHD performed in patients with bilateral or metastatic disease." (PMID 38664798, 2024). "One out of 10 patients with SDHD mutation had metastatic disease after a median follow-up duration of 12.1 years." (PMID 37434651, 2023). "We cultured 62 PPGLs, including tumours with confirmed SDHB, SDHC and SDHD variants, as well as several metastatic tumours." (PMID 36178902, 2022). "Metastatic disease is quite rare in patients with a SDHD mutation: a systematic review and meta-analysis reported a 4% pooled risk of malignant PPGL in SDHD mutation carriers in the prevalence studies." (PMID 33715142, 2021). "Meta-analyses have also been conducted in the other SDH variants, revealing the metastatic disease prevalence of 23% to 31% for SDHB, 23% for SDHC, 16% for SDHA, and 6% to 8% for SDHD." (PMID 41183483, 2026). "In contrast, they found 100% of cases were due to an SDHx PGV (six SDHB and four SDHD), 70% had catecholamine excess and 60% eventually developed metastatic disease." (PMID 40063004, 2025). "The algorithm for genetic testing did not fit in 3 out of the 24 patients with hereditary disease as we observed one case of metastatic disease (arteria renalis invasion) in a patient with a VHL mutation and positive SDHB staining in 2 SDHD-related PPGL." (PMID 37434651, 2023). "In total, 18 patients suffered from metastatic disease; germline mutations in SDHA, SDHB and SDHC were present in one patient each, while SDHD mutations were found in seven patients." (PMID 35171114, 2022). "Two patients with SDHB mutations and one patient with SDHD mutation were characterized by metastatic tumors but no SDHA variants were detected." (PMID 33391357, 2020). "Metastatic disease is one of the features that indicates likelihood of a hereditary cause, and it is recommended that patients with malignant PCC should undergo genetic testing for SDHB, SDHC, SDHD, VHL and MAX." (PMID 29768630, 2018). "Sensitivity analyses excluding studies with a mean time = 0 months (ie, metastatic disease at diagnosis) were performed for SDHB and SDHD." (PMID 41183483, 2026). "A 2012 meta-analysis estimated the pooled incidence of metastatic disease in SDHB carriers (with and without appreciable disease) at 17% and in SDHD carriers at 8%." (PMID 40063004, 2025). "Therefore, patients suspected of heritable HNPGLs should undergo genetic analysis first at the SDHD and SDHB loci, whilst if metastatic tumors or multiple abdominal paragangliomas are found without any familial presentation, the presence of SDHB mutations should be tested first." (PMID 34072806, 2021).
gastrointestinal stromal tumor (12 papers, 2012 to 2025). "Mutations in SDHD have been described in gastrointestinal stromal tumor (GIST), paraganglioma and pheochromocytoma." (PMID 26327518, 2015). "It comprises four subunits (SDHA, SDHB, SDHC and SDHD), any of which may be targeted in a subset of gastrointestinal stromal tumors (GIST) leading to SDH deficiency." (PMID 33921435, 2021). "Heterozygous germline mutations in SDH complex (SDHx) genes (SDHA, SDHB, SDHC, SDHD, and SDHAF2), which act as tumor suppressor genes, predispose to pheochromocytomas and paragangliomas (PPGLs) and rarely to gastrointestinal stromal tumors (GIST), renal cell carcinoma, and pituitary adenomas." (PMID 35892689, 2022).
renal cell carcinoma (11 papers, 2009 to 2025). "Studies have shown that SDHB and SDHD(Succinate dehydrogenase subunit D) mutations are present in renal cell carcinoma and thyroid tumors." (PMID 37749638, 2023). "F133-T1, whose histology was unclassified renal cell carcinoma, harboured a variant in succinate dehydrogenase D (SDHD), a gene responsible for SDH-associated tumour predisposition syndrome." (PMID 37182269, 2023). "Germline mutations within the Krebs cycle enzyme genes fumarate hydratase (FH) or succinate dehydrogenase (SDHB, SDHC, SDHD) are associated with an increased risk of aggressive and early metastasizing variants of renal cell carcinoma (RCC)." (PMID 36455002, 2022). "The kidney was chosen not only because of the more intense effect on SdhD deletion exerted by tamoxifen, but also due to the finding that renal cell carcinoma, although much less frequently, is also associated with Sdh-mutations." (PMID 24465590, 2014). "Mutations in protein subunits of succinate dehydrogenase (SDHA/SDHB/SDHC/SDHD and assembly factor SDHAF2) and fumarate hydratase (encoded by the single gene FH) lead to rare forms of renal cell carcinoma (RCC; denoted by SDHRCC and FHRCC, respectively)." (PMID 35288096, 2022). "Although we cannot exclude the possibility that methylation of regions other than the proximal promoter may be involved, our findings are also in keeping with others who have been unable to demonstrate methylation of SDHD in neuroblastomas and FH in renal cell cancers." (PMID 19778456, 2009).
von Hippel-Lindau syndrome (11 papers, 2005 to 2024). "Genetic information was available in 136 patients of the PHEO group, of whom 31.6% had a predisposing hereditary syndrome (27 MEN2A, 6 neurofibromatosis type 1, 4 SDHB mutations, 3 Von Hippel Lindau syndrome, 2 SDHD mutations and 1 patients MAX mutation)." (PMID 35177692, 2022). "Extra-adrenal pheochromocytomas can be associated with hereditary conditions such as multiple endocrine neoplasia (MEN) type 2, von Hippel-Lindau syndrome, or mutations in the SDHB, SDHD, or RET gene." (PMID 39867070, 2024). "The hereditary PHEO appears as a component of multiple endocrine neoplasia type 2 (MEN 2), von Hippel–Lindau disease (VHL), neurofibromatosis type 1 (NF1) or familial paraganglioma syndromes (caused by mutations of SDHD and SDHB genes)." (PMID 24675699, 2014). "Due to histopathologic diagnosis, genetic testing for familial paraganglioma, neurofibromatosis type 1, von Hippel-Lindau disease, the Carney triad, multiple endocrine neoplasia type 2, and mutations of the succinate dehydrogenase genes (SDHB, SDHC, and SDHD) was performed that was negative." (PMID 17683569, 2007).
neurofibromatosis type 1 (10 papers, 2007 to 2025). A clinically heterogeneous, neurocutaneous genetic disorder characterized by cafe-au-lait spots, iris Lisch nodules, axillary and inguinal freckling, and multiple neurofibromas. "Nine patients had a genetic syndrome, SDHB or SDHD-related PGL in seven, neurofibromatosis type 1 in two, four patients were classified as sporadic cases, and genetic testing had not been performed in nine patients." (PMID 31261748, 2019).
breast carcinoma (7 papers, 2009 to 2026). "SDHB and SDHD variants are highly related to the increased prevalence of breast cancers." (PMID 32156290, 2020). "Taken together, the elevated SDHD and METTL3 expression suggests a potential epigenetic mechanism-driven SDHD activation, highlighting its previously unreported role in breast cancer biology and revealing a distinct pattern of SDH dysregulation in the Bangladeshi breast cancer population." (PMID 41751859, 2026). "Interestingly, other types of malignancies (i.e. prostate cancer, lung cancer, breast cancer) are listed as causes of death both in the SDHB- and SDHD-linked cohorts." (PMID 30658386, 2019). "No DNA methylation was identified in the promoter regions of the SDHA, SDHB, SDHC, SDHD and FH genes in 72 breast carcinomas and 10 breast cancer cell lines using methylation-sensitive high resolution melting which detects both homogeneous and heterogeneous methylation." (PMID 19778456, 2009). "Indeed, 0.25% and 0.05% of breast cancer exomes carry somatic SDHB and SDHD variants, respectively." (PMID 30658386, 2019). "Different methods and different samples had been used in the two studies and our study, while there are four genes (PGK1, GCN1L1, PRDX5, and SDHD) that were repeated and identified at least twice in three studies and might become valuable prognostic tools or therapeutic targets in breast cancer." (PMID 26576432, 2015). "Since HIF-1α is frequently expressed in breast carcinomas, DNA methylation at the promoter regions of the SDHA, SDHB, SDHC and SDHD and FH genes was evaluated as a possible mechanism in silencing of SDH and FH expression in breast carcinomas." (PMID 19778456, 2009). "In conclusion, promoter methylation of the SDHA, SDHB, SDHC, SDHD and FH genes is unlikely to be an important mechanism in stabilising HIF-1 in breast carcinomas through the downregulation of the expression of SDH and FH genes." (PMID 19778456, 2009).
melanoma (7 papers, 2015 to 2020). A malignant, usually aggressive tumor composed of atypical, neoplastic melanocytes. "Recently, SDHD promoter mutations were reported in melanomas, associated with reduced gene expression and reduced patient survival." (PMID 28662141, 2017). "In this study, we assessed the presence of SDHD promoter mutations and SDHD protein expression in CM, OM and in melanoma cell lines, in which we already determined BRAF, NRAS, GNAQ and TERT promoter mutational status." (PMID 28662141, 2017). "We explored the putative association between SDHD protein expression and clinico-pathological and prognostic parameters of melanoma." (PMID 28662141, 2017). "In the present data set, we observe six mutated melanoma samples in the 5’ UTR of SDHD, which covers 135 bps." (PMID 28362259, 2017). "In our study of a large cohort of ocular, cutaneous, mucosal and occult melanomas, SDHD promoter mutations affecting recurrent ETS binding elements were identified in only 4% (16/400) of the samples." (PMID 26327518, 2015). "To explore the general frequency of SDHD promoter mutations and potential relevance for therapy resistance in melanoma, we re-analyzed exomes sequenced from 69 melanoma patients under MAPKi therapy." (PMID 26327518, 2015). "Our study analyzes the mutation rate and clinico-pathologic associations of SDHD promoter mutations in a large cohort of different melanoma subtypes." (PMID 26327518, 2015). "Should these findings be validated in additional cohorts, they argue that compared to the much more frequent and prognostically relevant TERT promoter mutations, SDHD promoter mutations play a relatively minor role in melanoma." (PMID 26327518, 2015). "Melanomas harbor recurrent SDHD promoter mutations, which occur primarily as C>T alterations in UV-exposed melanomas." (PMID 26327518, 2015). "In contrast to the initial report and promoter mutations in the TERT gene, our analysis suggests that SDHD promoter mutations are a relatively rare event in melanoma (4% of tumors) of unclear clinical and prognostic relevance." (PMID 26327518, 2015). "In addition to TERT promoter mutations, a less well-described mutation in the succinate dehydrogenase complex subunit D (SDHD) promoter has been observed in melanoma." (PMID 33024276, 2020). "SDHD was expressed not only in melanocytes/melanoma cells, but also in keratinocytes and in the cells of sebaceous glands and hair follicles." (PMID 28662141, 2017). "We assessed SDHD promoter status in cutaneous melanomas (CM), ocular melanomas (OM) and melanoma cell lines, and the expression of SDHD protein by immunohistochemistry in CM and OM, and by western blot in melanoma cell lines." (PMID 28662141, 2017). "A recent study identified the promoter region as well as the 5’ UTR of SDHD to be potential cancer drivers in melanoma." (PMID 28362259, 2017). "SDHD protein was expressed in all melanoma cell lines analysed and in all CM cases, including the two cases with SDHD mutation." (PMID 28662141, 2017). "None of the OM cases,cutaneous (n = 4) and ocular (n = 7) melanoma cell lines studied harboured any alteration in the promoter of the SDHD gene." (PMID 28662141, 2017). "Unlike mutations in the TERT promoter, mutations in the SDHD promoter were found exclusively in melanoma and not in other cancer types." (PMID 33024276, 2020). "SDHD promoter mutations that abolished ETS-binding sites in melanoma cells resulted in significantly lower SDHD expression compared with that in melanoma cells without SDHD promoter mutations." (PMID 33024276, 2020). "In particular, the non-coding mutations in the succinate dehydrogenase complex, subunit D, integral membrane protein (SDHD) and diphthamide biosynthesis 3 (DPH3) promoters have been shown to affect Ets binding motifs and occurred in melanoma at frequencies of 4-10 and 13%, respectively." (PMID 26416425, 2015).
melanoma (continued). "The type of mutations identified does support SDHD promoter mutations in UV-exposed tumors (i.e. non-acral cutaneous) being primarily UV-induced, whereas the 542C>A mutation occurring in a mucosal, non UV-exposed melanoma probably developed in a UV-independent fashion." (PMID 26327518, 2015). "The SDHD promoter was successfully sequenced in 451 melanoma samples available for analysis, including 223 non-acral cutaneous, 38 acral, 33 mucosal, 43 occult, 43 conjunctival and 51 uveal melanoma samples." (PMID 26327518, 2015).